SFRP2 (secreted frizzled related protein 2)
Diseases named in the same sentence as SFRP2 in open-access papers (continued):
Sharing a sentence is not in itself a finding about the gene and the disease.
psoriasis (8 papers, 2012 to 2025). An autoimmune condition characterized by red, well-delineated plaques with silvery scales that are usually on the extensor surfaces and scalp. "In murine skin, a population of inflammatory fibroblasts that shared similarities with SFRP2+ fibroblasts and expressed genes associated with psoriasis-related inflammation was identified." (PMID 38545113, 2024). "SFRP2+ fibroblasts have been identified as essential cells in psoriasis pathogenesis, which impacts other spatially proximate cell types by producing chemokines." (PMID 38545113, 2024). "The SFRP2+ inflammatory fibroblasts in psoriasis appear analogous to an inflammatory fibroblast population in murine skin, with the latter expressing Camp58, encoding an antimicrobial peptide that contributes to inflammation in psoriasis." (PMID 37308489, 2023). "We further show that a subset of SFRP2+ fibroblasts in psoriasis contribute to amplification of the immune network through transition to a pro-inflammatory state." (PMID 37308489, 2023). "We observed the upregulation of CMKLR-1, COL8A-1, NETO-2, NRK, SYTL-2, and SULF-2 in dermal mesenchymal stem cells derived from patients with psoriasis at both mRNA and protein level, however, a significant downregulation of SFRP-2 between two groups." (PMID 30760317, 2019). "We observed significant increases in protein expression of CMKLR-1, COL8A-1, NRK, and SYTL-2 in DMSCs from patients with psoriasis compared with those from healthy donors, whereas the expression level of SFRP-2 was obviously decreased." (PMID 30760317, 2019). "Interestingly, SFRP2+ inflammatory fibroblasts in psoriasis and COL6A5+ COL18A1+ fibroblasts in atopic dermatitis express CCL19, which can recruit CCR7+ LAMP3+ type 2 conventional dendritic cell (cDC2)." (PMID 38545113, 2024). "In addition, the SFRP2+ inflammatory fibroblasts in psoriasis share with the COL6A5+COL18A1+ fibroblasts in atopic dermatitis the expression of CCL19 which is capable of recruiting CCR7+LAMP3+ cDC2A61." (PMID 37308489, 2023). "In psoriasis, SFRP2+ fibroblasts transition from a fibrotic to an inflammatory state." (PMID 37308489, 2023). "SFRP2+ fibroblasts were reported to overexpress ERAP2 and HLA-C in psoriasis." (PMID 40574847, 2025). "In the present study, the downregulation of SFRP2 and overexpression of CMKLR, COL8A, NRK, and SYTL2 reported herein revealed enhanced migratory and invasive potential abilities from DMSCs to other cells in psoriasis, which may be beneficial to the immunomodulatory properties of MSCs." (PMID 30760317, 2019). "However, the repression of Wnt3 as well as the dysregulation of SFRP1 and SFRP2 are only found in invasive cutaneous SCC, but not psoriasis." (PMID 22384081, 2012).
diabetes mellitus (7 papers, 2016 to 2025). A metabolic disorder characterized by abnormally high blood sugar levels due to diminished production of insulin or insulin resistance/desensitization. "The association of sFRP2 with cardiac fibrosis and with malignant neoplasms represents a potential common aetiology for the association of insulin resistance and diabetes with heart failure and with cancer." (PMID 27685706, 2016). "At last, to evaluate whether this association between SFRP2 methylation and therapy could be due to other potential confounder variables, we performed a multivariable analysis, including age, BMI and presence of diabetes mellitus." (PMID 31319558, 2019). "Our study addresses a critical gap in understanding the renal-osteal crosstalk in diabetes by demonstrating that glomerular MCs serve as a major endocrine source of circulating secreted SFRP2 in DKD." (PMID 41030909, 2025). "Our findings verified the value of SFRP2 in a novel mitochondria-relevant mechanism that mediated cardioprotection via activation of the AMPK-PGC1-α signaling pathway in the diabetes-induced cardiac dysfunction." (PMID 34790288, 2021). "In addition, we also found that cardiomyocyte apoptosis was exacerbated by diabetes mellitus, while treatment with SFRP2 reduced cardiac cell apoptosis." (PMID 34790288, 2021). "We aimed to determine the serum levels of sFRP2 in patients at different stages of heart failure (HF) with or without type 2 diabetes mellitus (T2DM), and assess the correlation between circulating sFRP2 levels and cardiometabolic risk factors." (PMID 34722660, 2021).
heart failure (6 papers, 2016 to 2025). Inability of the heart to pump blood at an adequate rate to meet tissue metabolic requirements. "Combined with our early findings, it is more supportive that SFRP2 is a compensatory protective response of heart failure." (PMID 34790288, 2021). "In animal models of heart failure, sFRP2 expression was increased, and blockade of sFRP2 using an antibody resulted in improved left ventricular ejection fraction." (PMID 27685706, 2016). "Transcript levels of several established biomarkers, including Spp1, Sfrp1, Sfrp2, Tnc, Vim, Mmp9, and Tnfrsf1a, and several inflammatory markers that are known to be activated in heart failure, such as Cd44, Cd83, Ccl7, Irf7, and Nr4a2, were upregulated in the Myh6-McmTamDspfl/fl cardiomyocytes." (PMID 40608429, 2025).
bladder cancer (5 papers, 2008 to 2025). "Intriguingly, the violin plots showed that both the mRNA levels of SFRP1 and SFRP2 significantly increase with the progression of bladder cancer (from stage II to stage IV)." (PMID 35372028, 2022). "In a recent bladder cancer study FGFR3 mutation in combination with APC, RASSF1A, and SFRP2 methylation markers provided a sensitivity of 90% using tissue samples and 62% using paired urine samples to identify the presence of cancer with 100% specificity." (PMID 22530128, 2012). "As discussed by Serizawa, results also showed that FGFR3 mutation in bladder cancer when combined with methylation markers (APC, RASSF1A and SFRP2) provided a sensitivity of 90% to identify bladder tumors." (PMID 22530128, 2012). "Interestingly, the violin plots showed that both the mRNA levels of SFRP1 and SFRP2 significantly increase with the progression of bladder cancer (from stage II to stage IV)." (PMID 35372028, 2022). "Of these miRNAs, miR-218 has been reported to be downregulated in bladder cancer, which suggests that increased SFRP2 transcripts may attribute to miR-218 downregulation in UC." (PMID 35372028, 2022). "In bladder cancer, SFRP2 methylation was shown to represent an independent predictor of malignancy, although in multivariate logistic regression analysis it was not a reliable biomarker because of a limited sensitivity/specificity due to some extent of methylation in normal bladder mucosa." (PMID 18990230, 2008). "However, we observed that both the SFRP1 and SFRP2 mRNA levels are not inversely correlated with their methylation status using the TCGA bladder cancer database (n = 413)." (PMID 35372028, 2022).
diabetic cardiomyopathy (5 papers, 2021 to 2025). Diabetic cardiomyopathy is a disorder of the heart muscle in people with diabetes. "Secreted frizzled-related protein 2 (SFRP2) that interfere with Wnt is known to modulate mitochondrial dynamics and mitochondrial biogenesis as well as exert cardioprotective effects within diabetic cardiomyopathy." (PMID 35783193, 2022). "Given the important role of mitochondrial fusion in diabetic cardiomyopathy, we speculate that SFRP2 may regulate and improve mitochondrial fusion to reduce cardiomyocyte damage caused by high glucose." (PMID 34790288, 2021). "Secreted frizzled-related protein 2 (SFRP2), a novel adipokine, has demonstrated cardioprotective effects in diabetic cardiomyopathy." (PMID 40004130, 2025).
hepatocellular carcinoma (5 papers, 2017 to 2023). A malignant tumor that arises from hepatocytes. "The levels of SFRP1, SFRP2, and SFRP5 methylation were also reported up-regulated in hepatocellular carcinoma tissues." (PMID 34205081, 2021). "Overexpression of miR‐522 could promote proliferation of hepatocellular carcinoma through repressing DKK1 and SFRP2." (PMID 33369228, 2021). "In hepatocellular carcinoma (HCC), SFRP genes are frequently inactivated, and this is also observed in premalignancy, with SFRP2 predicted to be inactivated by promoter hypermethylation in 33% and 42% of HBV-driven and HCV-driven hepatitis samples, respectively." (PMID 37298494, 2023). "Secreted frizzled related proteins (SFRP1, SFRP2, SFRP3), which are Frizzled competitors for Wnt, are silenced by promoter hypermethylation in different cancers, including hepatocellular carcinoma (HCC), lung adenocarcinoma, oesophageal squamous cell carcinoma (ESCC) and CRC." (PMID 28931650, 2017).
Obesity (5 papers, 2019 to 2021). Accumulation of substantial excess body fat. "FA treatment decreased mRNA of ApoD, SEMA3C, CXCL12, and sFRP2, which are closely related to adipocyte differentiation and obesity." (PMID 33915783, 2021). "In SAT, sFRP-1 was decreased and sFRP-2 increased in obesity and accordingly, sFRP-1 negatively, while sFRP-2 positively associated with insulin resistance." (PMID 32218328, 2020). "This study was aimed to evaluate the effect of obesity, measured by BMI, on the methylation of SFRP2 in tumor samples of patients with CRC." (PMID 31319558, 2019). "Mechanistic studies are needed to investigate whether proteins such as SFRP2, HILPDA, and SCD mediate associations between obesity and its comorbidities." (PMID 30884788, 2019). "In essence, the functional role of SFRP2 in CRC and its potential influence through an increased BMI, could explain, at least partially, the process through which obesity and Wnt/β catenin might exert their effect on carcinogenesis through independent molecular pathways." (PMID 31319558, 2019).
fibrosis (4 papers, 2013 to 2024). the formation of excess fibrous connective tissue in an organ or tissue in a reparative or reactive process. "Of 3016 SNPs evaluated, eight were significantly associated with fibrosis risk (e.g., SFRP2 rs11937424: OR = 2.19, 95% CI 1.48-3.23, P = 0.00004), and seven were significantly associated with inflammation risk (e.g., SFRP1 rs16890282: OR = 2.15, 95% CI 1.39-3.16, P = 0.0004)." (PMID 24386373, 2013). "Secreted frizzled-related protein 2 (sFRP2), a vital modulator in Wnt signaling,plays an important role in cardiac remodeling caused by hypoxia,hypoxia-reoxygenation (HR), pressure overload, and autoimmunemyocarditis through regulating cardiac fibrosis, hypertrophy, cell death,and regeneration." (PMID 39076470, 2024). "Cluster 10 (fibroblast-Wif1) showed increased expression of genes (Wif1, Dkk3, Sfrp1, Sfrp2) involved in negative regulation of Wnt signaling pathway, which has been considered to inhibit cardiac fibrosis." (PMID 36805782, 2023). "Despite the reported biphasic effects of Sfrp2 on cardiac fibrosis, our studies revealed a protective role of Sfrp2 knockdown in TGF‐β-induced fibrosis, consistent with previous studies in Sfrp2-deficient mice." (PMID 31695768, 2019).
Insulin resistance (4 papers, 2016 to 2021). Increased resistance towards insulin, that is, diminished effectiveness of insulin in reducing blood glucose levels. "Adipose tissue expression of sFRP2 has been associated with insulin resistance, and this study defined serum sFRP2 as an adipokine strongly associated with abnormal glucose tolerance and increased insulin secretion." (PMID 27685706, 2016). "sFRP2 was reported to be associated with lipogenesis and insulin resistance, which indicated that sFRP2 might modulate heart function via regulating metabolism." (PMID 34722660, 2021). "It is possible that sFRP2-mediated adipose tissue expansion and insulin secretion is a potential compensatory mechanism in the setting of visceral adiposity and insulin resistance." (PMID 27685706, 2016). "Recently, mRNA expression of 5 sFRP family members was characterised in human AT where the sFRP2 mRNA levels in subcutaneous adipose tissues were positively correlated with insulin resistance." (PMID 27685706, 2016). "Serum sFRP2 was positively associated with circulating insulin, homeostasis model assessment of β cell secretory capacity (HOMA-β) and insulin resistance (HOMAIR), body mass index (BMI) and triglycerides (TG), and was increased in patients with abnormal glucose tolerance (AGT)." (PMID 34722660, 2021). "SFRP2 methylation in tumor area was decreased in patients who had higher levels of vitamin D. SFRP2 promoter methylation was positively correlated in tumor area with insulin and homeostasis model assessment of insulin resistance (HOMA-IR) but negatively correlated with HDL-c." (PMID 32517740, 2020). "Thus, SFRP2 was related to insulin sensitivity and insulin resistance." (PMID 32517740, 2020).
metastatic tumors (4 papers, 2016 to 2023). "To validate our initial expression profiling data, we performed qPCR of independent local and primary metastatic mouse tumors and noted significant enhanced expression of sFRP2 in the metastatic tumors." (PMID 27821163, 2016).
oral squamous cell carcinoma (4 papers, 2014 to 2021). "Loss of SFRP2 expression is also found in oral squamous cell carcinoma, and SFRP2 overexpression inhibits proliferation, cell cycle progression, and tumor growth by increasing the expression of GSK-3β and β-catenin." (PMID 34852024, 2021). "The role of epigenetic inactivation of secreted frizzled-related protein 2 (SFRP2) and its functions in the development of oral squamous cell carcinoma (OSCC) remain to be elucidated." (PMID 25189527, 2014). "In the first stage, 16 oral squamous cell carcinoma cell lines were screened for the methylation of DACH1, DKK1, LKB1, PPP2R2B, RUNX3, SFRP2, and WIF-1 using methylation-specific PCR." (PMID 25487617, 2015). "The methylation of DACH1, DKK1, LKB1, PPP2R2B, RUNX3, SFRP2, and WIF-1 was analyzed in 16 oral squamous cell carcinoma cell lines using the methylation-specific polymerase chain reaction." (PMID 25487617, 2015).
osteoporosis (4 papers, 2013 to 2025). A condition of reduced bone mass, with decreased cortical thickness and a decrease in the number and size of the trabeculae of cancellous bone (but normal chemical composition), resulting in increased fracture incidence. "Raloxifene which is ranked 4th as an SFRP2-down-regulator, is a selective estrogen receptor modulator used to treat osteoporosis in women who are at an increased risk of this disorder with age." (PMID 36100892, 2022). "Sfrp2 is an osteoporosis susceptibility gene associated with bone mineral density." (PMID 24116037, 2013). "Whether SFRP2 serum level can serve as both a diagnostic indicator and a therapeutic target for DKD-related osteoporosis merits further investigation." (PMID 41030909, 2025). "Here, we integrate single-cell profiling of diabetic kidney and exosome-based functional intervention to test the hypothesis that MC-derived SFRP2 exacerbates osteoporosis, and reducing SFRP2 expression could serve as an effective therapeutic approach." (PMID 41030909, 2025). "It is thus interesting to explore whether Sfrp2 from these organs also elevates and contributes to osteoporosis in DKD." (PMID 41030909, 2025).
pituitary adenomas (4 papers, 2015 to 2024). "SFRP2 expression appears to be involved in tumor aggressiveness and invasiveness, as indicated by the most significant SFRP2 downregulation in aggressive and invasive pituitary adenomas compared to less aggressive or invasive tumor types." (PMID 39850884, 2024). "However, SFRP2 and 4 (secreted-frizzled related protein), Wnt antagonists, considered as tumor suppressor genes, were downregulated in pituitary adenomas, in particular in invasive tumors, suggesting a role of the Wnt pathway in the progression of PitNETs." (PMID 35203352, 2022). "SFRP2 expression also seems to be involved in tumor aggressiveness and invasiveness, indicated by the largest SFRP2 downregulation in aggressive and invasive pituitary adenoma compared to their less aggressive or invasive tumor types, respectively." (PMID 33140138, 2021). "A review of 13 whole genome approaches in pituitary tumors with the goal of identifying Wnt family inhibitors showed that expression of WF1, SFRP2, FRZB, SFRP4, DKK2, and SOSTDC1 genes is decreased in pituitary adenomas compared to normal pituitary tissue, while that of SFRP1 and SFRP4 is increased." (PMID 25834571, 2015).
pulmonary fibrosis (4 papers, 2022 to 2026). Chronic progressive interstitial lung disorder characterized by the replacement of the lung tissue by connective tissue, leading to progressive dyspnea, respiratory failure, or right heart failure. "Furthermore, therapeutic intervention with AAV6-shSfrp2, SFRP2-neutralizing antibody, or the autophagy inducer rapamycin significantly ameliorated lung fibrosis in bleomycin (BLM)-induced mouse models." (PMID 41789512, 2026). "sFRP2 is an interesting protein relevant to pulmonary fibrosis in several respects." (PMID 38980870, 2024). "To further verify the differential expression of candidate hub genes between IPF and control samples, we then established a bleomycin-induced pulmonary fibrosis mouse model and detected the expression of SLCO4A1, ASPN and SFRP2 between fibrotic lung samples and control samples from model mice." (PMID 37334348, 2023).
renal cell carcinoma (4 papers, 2014 to 2021). "Transient transfection of SFRP2 in renal cell carcinoma has been shown to increase tumor growth in vivo." (PMID 24489757, 2014). "As for renal cell carcinoma, low levels of AcH3, AcH4 and H3K4 and a high level of H3K9, known as repressive histone modifications, were found in the SFRP2 negative cell lines." (PMID 28422739, 2017).
ameloblastoma (3 papers, 2017 to 2024). The most common odontogenic tumor, arising from the epithelial component of the embryonic tooth and usually affecting the molar-ramus region of the mandible or maxilla. "In addition, SFRP2 was found to be strongly expressed in ameloblastoma tissues and AM-1 cells." (PMID 28794794, 2017).
bladder tumors (3 papers, 2012 to 2022). "The methylation levels of sFRP-2 and Dkk-3 were found to be significant independent predictors of bladder tumors, whereas with sFRP-1, sFRP-5, and Wif-1, a trend towards significance was found as independent predictors." (PMID 22325146, 2012). "Another study demonstrated higher promoter CpG hypermethylation and lower expression of mRNA transcripts for sFRP-1, sFRP-2, sFRP-4, and sFRP-5, Dkk-3, and Wif-1 genes in bladder tumor compared with normal bladder mucosa showing an inverse correlation." (PMID 22325146, 2012). "However, only bladder tumors with high mRNA level of SFRP2 (n = 101) significantly conferred inferior overall survival compared with those with low SFRP2 mRNA level (n = 100) (p = 0.00052)." (PMID 35372028, 2022).
cardiac hypertrophy (3 papers, 2016 to 2024). "Here, the authors show that blocking Ca2+ signaling controlled by the transport protein PMCA4 in cardiac fibroblasts enhances secretion of a potent Wnt signaling inhibitor, sFRP2, and prevents the development of pathologic cardiac hypertrophy in mice." (PMID 27020607, 2016). "We also show that targeting PMCA4 by a novel inhibitor is beneficial to the progression of cardiac hypertrophy probably through potentiation of sFRP2 production." (PMID 27020607, 2016). "Overexpression of sFRP2 attenuates cardiac hypertrophy by targeting theWnt/β-catenin pathway." (PMID 39076470, 2024).
colorectal adenoma (3 papers, 2015 to 2021). An adenoma that arises from the colon or rectum. "In addition, it was reported that the sensitivity of the combined study using three methylation markers of ITGA4, SFRP2 and p16 in stool samples for colorectal adenoma detection was 72.0% at 96.8% specificity." (PMID 33391430, 2021).